NOTCH3 (notch receptor 3)
Diseases named in the same sentence as NOTCH3 in open-access papers (continued):
Sharing a sentence is not in itself a finding about the gene and the disease.
breast carcinoma (continued). "Using the same E0771 mammary tumor cells and several human breast cancer cell lines we recently reported that when exposed to leptin, breast cancer cells express higher protein levels of Notch 3, as we also found in the present study in macrophages exposed to low leptin concentrations." (PMID 25599228, 2015). "IL-6 mRNA is detectable only in basal-like breast carcinoma tissues; our results reveal that IL-6 triggers a Notch-3-dependent upregulation of the Notch ligand Jagged-1, whose interaction with Notch-3 promotes the growth of MS and Michigan Cancer Foundation-7 (MCF-7)-derived spheroids." (PMID 25881039, 2015). "In contrast to the more differentiated breast cancer cell lines, Notch4 was readily detectable in the ES cells, whereas Notch3 expression levels were difficult to detect, reflecting the known expression patterns and functional roles of these two genes in differentiation and development." (PMID 23863842, 2013). "Furthermore, LLL12 inhibited Twist1, Notch-1, and Notch-3 expression in ALDH+ breast cancer stem-like cells, which have recently been reported as STAT3 or Interleukin-6 target genes." (PMID 24376586, 2013). "Interestingly, the expression of STAT5A is similar to Notch3 levels in breast cancer cell lines." (PMID 38124049, 2023). "However, a phase I clinical trial of PF-06650808, a Notch3-specific antibody–drug conjugate, has demonstrated a reasonable safety profile and early efficacy signs of antitumor activity in patients with advanced breast cancer." (PMID 37149651, 2023). "Furthermore, Notch3 can inhibit EMT in breast cancer epithelial cells by transactivating GATA3." (PMID 36139447, 2022). "We believe that the Notch3-PTEN axis may be a prospective prognostic predictor for breast cancer." (PMID 34006834, 2021). "However, NOTCH3 overexpression does not fully recapitulate the effect of CBFB loss-of-function in breast cancer, suggesting that other mechanism(s) also contribute to the tumor suppressive function of CBFB." (PMID 33945523, 2021). "Thus, the NOTCH3 output in luminal A breast cancer may be determined by the activity of kinases such as PIM that phosphorylate N3ICD at serine 1672." (PMID 33775697, 2021). "Investigations on the association of NOTCH1 rs3124591, NOTCH3 rs1043994, and NOTCH4 rs3830041 with the risk of human cancers are rare, however, several studies have shown a link between NOTCH2 related rs11249433 and increased risk of breast cancer especially in women of European ancestry." (PMID 34257585, 2021). "Similarly, Notch3 has been found to inhibit breast cancer cell EMT." (PMID 34295896, 2021). "Recently, some studies reported different molecular mechanism by which Notch3 seems to inhibit EMT in breast cancer, including TNBCs, but overall high transcript levels of Notch3 were associated with less distant metastasis and better prognosis only in ER+ breast cancer." (PMID 31379945, 2019). "Because we have previously demonstrated the causative role of aberrant AURKA activity in driving the development of breast cancer metastases, we aimed to establish whether NOTCH3 expression was required to mediate AURKA-induced highly invasive capacity of vMCF-7∆Raf1 1GX cells." (PMID 30180881, 2018). "Furthermore, NOTCH2 and NOTCH3 amplifications are found in basal breast cancers." (PMID 30388742, 2018). "However, given the emerging evidence that Notch receptors have distinct activities and functions in different tissues, Notch3 may have a unique role in breast cancer cells." (PMID 30100605, 2018). "To validate in primary breast cancer cells the central role of the NOTCH3 signaling pathway in inducing a metastatic phenotype, we developed unique TNBC cells (TNBC-M25) isolated from a patient-derived brain metastasis xenograft model that was generated by the BEAUTY trial in the Mayo Clinic." (PMID 30180881, 2018). "Several recent studies have reported that mutations in NOTCH3 and NOTCH4 may cause breast cancer." (PMID 28977883, 2017).
breast carcinoma (continued). "In addition, NOTCH3 activation has been detected in various breast cancer cell lines." (PMID 27888801, 2017). "Here, we present solid evidence that Notch3 can act as a tumor suppressor in breast cancer epithelial cells, that the loss of Notch3 is an important feature of TNBC, and that Notch3 inhibits EMT by activating the Hippo/yes-associated protein (YAP) pathway mediated by Kibra in breast cancer." (PMID 27841855, 2016). "Since we have reported that i21VEGFR-1 can activate Src and increase the invasiveness of MDA-MB-231 cells, Notch-1 and Notch-3 signaling pathways could contribute to the invasive phenotype of MDA-MB-231 breast cancer cells through upregulation of i21VEGFR-1 protein." (PMID 24709904, 2014). "These included several well-known cancer genes or their family members with previously less recognized role in breast cancer—FGFR3, FGFR4, NOTCH3, KMT2B, EP300, FLT4 and FAT1." (PMID 40858906, 2025). "The current study aims to evaluate the correlation between NOTCH3 and ZEB1 and investigate the potential regulatory axis in breast cancer." (PMID 38164285, 2024). "Clinically, high expression of NOTCH3, miR-223 or low expression of ZEB1 were related to good prognosis of breast cancer patients." (PMID 38164285, 2024). "In any case, based on these results, we found that NOTCH3 is abnormally highly expressed in gastrointestinal tumors (COAD, LIHC, PAAD, STAD), breast cancer and lung cancer, and increased NOTCH3 expression was associated with poor prognosis." (PMID 38906903, 2024). "NOTCH3 maintains the luminal phenotype and inhibits epithelial-mesenchymal transition (EMT) in breast cancer, while ZEB1 and NOTCH3 have the opposite effects." (PMID 38164285, 2024). "It was found that the expressions of NOTCH3 and ZEB1 in breast cancer cells were negatively correlated." (PMID 38164285, 2024). "In order to further explore the expression pattern of NOTCH3 and ZEB1 in breast cancer, online databases CCLE and THPA were mined to analyze the expression of NOTCH3 and ZEB1 in different breast cancer cell lines." (PMID 38164285, 2024). "In the patient breast cancer dataset (GSE43095), we observed an increased methylation of the Notch3 promoter in tumor samples compared to normal tissue." (PMID 36854682, 2023). "Previous studies have also shown that circ-NOTCH3 and the long non-coding RNA NEAT1 can promote breast cancer development by up-regulating KLF12 expression." (PMID 37156774, 2023). "In the current study, STAT5A was first shown to be activated by Notch3 signaling in breast cancer, resulting in suppression of EMT and metastasis of breast cancer cells." (PMID 38124049, 2023). "PD‐L1 expression on breast cancer stem cells was partly dependent on Notch via PI3K/AKT pathway, and Notch3 as a mediator for PD‐L1 was important for maintaining stemness." (PMID 36971192, 2023). "To verify the impact of Notch3 expression in cancer versus stromal cells (fibroblasts), we analyzed a TMA containing 117 samples of breast cancer patients." (PMID 36854682, 2023). "Therefore, Notch3 may have a pivotal role in tumor suppression, especially in breast cancer EMT." (PMID 36139447, 2022). "Direct or indirect interactions have been shown between these two signaling pathways; however, the relationship between Notch3 and GSK3β in EMT of breast cancer is still unclear." (PMID 36139447, 2022). "In breast cancer, MCF-7 and MDA-MB-231 cell lines, the silencing of Notch3 reduced GSK3β expression, which is sufficient to induce EMT." (PMID 36139447, 2022). "In a prognostic analysis, high expression of mRNA of both Notch3 and GSK3β was related to better RFS in all patients with breast cancer studied, which implies that Notch3 and GSK3β are beneficial biomarkers in this disease." (PMID 36139447, 2022). "Notch3 was found to inhibit EMT by directly binding to the GSK3β promoter and transactivating GSK3β in breast cancer." (PMID 36139447, 2022).
breast carcinoma (continued). "NOTCH3 signaling plays a carcinogenic role in solid tumors, including CRC, breast cancer, and lung cancer." (PMID 35900231, 2022). "Pertinent to our study, Notch3 was found to transactivate GSK3β and to inhibit EMT in a breast cancer cell model." (PMID 36497426, 2022). "Notch3 and Jag1 are key regulators of CSC renewal and survival during hypoxia in breast cancer and tumours derived from breast cancer cell lines." (PMID 35563449, 2022). "In a breast cancer cell line, exposure to hypoxic environment induced 66 kDa isoform of the SHC gene (p66Shc), which controls the expression of Notch-3." (PMID 36017236, 2022). "High expression of Notch3 (p = 4.1 × 10−7) and GSK3β (p = 3.8 × 10−5) mRNAs correlated with an improved RFS for all patients with breast cancer." (PMID 36139447, 2022). "To further investigate the role of Notch3 and PTEN in breast cancer, we evaluated their protein and mRNA expression levels in breast cancer cell lines representing distinct subtypes." (PMID 34006834, 2021). "After establishing TAp73 induction as another mechanism, we explored the relationship between TAp73 and the NOTCH3 intracellular domain (NICD)—the active part of NOTCH3 involved in transcriptional regulation and oncogenic transformation of breast cancer." (PMID 33945523, 2021). "The prognosis of Notch3- and PTEN-positive breast cancer patients across different subtypes was estimated from the Kaplan–Meier Plotter clinical database." (PMID 34006834, 2021). "In this study, we found that Notch3 and PTEN levels correlated with the luminal phenotype in breast cancer cell lines." (PMID 34006834, 2021). "We also evaluated the effects of modulating Notch3 and PTEN expression on breast cancer cell proliferation using the colony formation assay." (PMID 34006834, 2021). "In a single cell gene expression analysis, NOTCH4, NOTCH3 and JAG1 were upregulated in metastatic breast cancer cells compared to primary tumour cells isolated from TNBC patient-derived xenograft (PDX) models." (PMID 34295896, 2021). "To determine the potential regulation between Notch3 and PTEN, we knocked down or overexpressed these two genes in breast cancer cells." (PMID 34006834, 2021). "Our current study firstly demonstrates that Notch3 transcriptionally upregulates PTEN and its downstream pathway by binding to the CSL elements in the PTEN promoter, and leads to the inhibition of breast cancer cell proliferation and migration/invasion." (PMID 34006834, 2021). "In conclusion, Notch3 and PTEN mRNA overexpression were indicative of a good prognosis for breast cancer patients." (PMID 34006834, 2021). "Both Notch3 and FSCN1 expression were statistically related to the subtypes of breast cancer divided by ER, PR, and HER2 status (p = 0.001 and 0.012, respectively)." (PMID 33099573, 2020). "The NOTCH family genes, including NOTCH1, NOTCH2, NOTCH3, and NOTCH4, are highly expressed in breast cancer patients." (PMID 33324444, 2020). "Our findings illustrated that Notch3-regulating CCL2/CCR4 axis should be an important signaling pathway for mammary gland development and should be a candidate target for breast cancer therapy." (PMID 33244467, 2020). "In line with previous data, the relevance of co-operation between the intracellular domain of Notch-3 (NICD) and HIF-1α for CA9 expression (at the level of mRNA, protein, and reporter) was described in breast cancer cells." (PMID 32707920, 2020). "We found that protein and mRNA level of Notch3 and GATA-3 was positively correlated especially in luminal breast cancer cells." (PMID 32636747, 2020). "The primary findings of this current study provide critical insights into the crucial role of the Notch3/miR-488/FSCN1 axis in EMT and metastasis of breast cancer." (PMID 33099573, 2020). "This paracrine anti-viral and juxtacrine NOTCH3 pathways converge, leading to facilitation of STAT1 transcriptional responses to NOTCH3 thus expanding therapy resistant breast cancer cells." (PMID 31146452, 2019).
breast carcinoma (continued). "First of all, it is already ascertained that Notch3 has transforming potentials in vivo, since transgenic mice overexpressing the intracellular domain of Notch3 (N3ICD) developed breast cancer." (PMID 31379945, 2019). "We demonstrate in vitro and in vivo that Notch3 suppressed EMT and breast cancer metastasis by activating GATA-3 transcription." (PMID 30100605, 2018). "To explore the possible roles for Notch3 and GATA-3 in breast cancer, we detected their expression levels in a series of breast cancer cell lines." (PMID 30100605, 2018). "In the present study, we present solid evidence demonstrating that activated Notch3 maintains the epithelial phenotype and suppresses metastasis through the transcriptional regulation of GATA-3 in breast cancer." (PMID 30100605, 2018). "Our results provide novel insights into the complex regulation of EMT and provide a basis for further delineation of the Notch3/GATA-3 pathway as a promising candidate of prognostic indicator and/or therapeutic avenue for breast cancers." (PMID 30100605, 2018). "Altogether, we have presented evidence dissecting the role of the Notch3/GATA-3 axis in the EMT process, as well as in the inhibition of breast cancer metastasis." (PMID 30100605, 2018). "We further interrogated Notch3 and GATA-3 mRNA in several breast cancer cell lines to validate results at the protein level." (PMID 30100605, 2018). "To date, there have been few investigations into the specific connection between Notch3 and GATA-3 in breast cancer cells." (PMID 30100605, 2018). "To examine miR-221 and miR-222’s roles in regulating Notch3 and EMT, we transfected synthetic oligo mimics for miR-221 and miR-222 into MCF-7 breast cancer cells." (PMID 30109262, 2018). "On the other hand, Notch3 is constitutively activated in one third of basal-like breast cancers, and a Notch3 specific antagonistic antibody, anti-N3.A4, hampered the growth of orthotopic HCC1143 breast cancer xenografts in mice." (PMID 29462871, 2018). "Herein, we demonstrate a novel mechanism whereby Notch3 inhibit EMT by transcriptionally upregulating GATA-3 expression, at least in part, leading to the suppression of cancer metastasis in breast cancers." (PMID 30100605, 2018). "We identified four genes that were overexpressed in cluster 2 cells—KRT7, NOTCH3, CD146, and YAP1—and analyzed publicly available expression data to assess the relevance of these genes in breast cancer." (PMID 29606612, 2018). "Together, these findings suggest a functional and positive correlation between Notch3 and GATA-3 during EMT in breast cancer." (PMID 30100605, 2018). "The study also evaluated the influence of the ADAM10, NOTCH1, NOTCH3, HES1, LFNG and PSEN1 genes on breast cancer recurrence." (PMID 27888801, 2017). "In contrast, some ERα+ breast cancer cell lines with low proliferation rates, such as MCF-7 and T47D, presented higher expression levels of Notch3 and E-cadherin." (PMID 27841855, 2016). "A working model is proposed for breast cancer cells, particularly TNBC cells, in which there exists complex inter-related and inter-dependent correlation between Kibra and Notch3." (PMID 27841855, 2016). "Target genes of miR-206 are MET in RMS; estrogen receptor 1 (ESR1, alias; ERα) in breast cancer and EEC; and notch 3 (NOTCH3) in HeLa cells." (PMID 22308266, 2012). "In breast cancer—particularly triple−negative breast cancer—the Notch3/mTOR/HIF−1 signaling axis enhances glycolysis and thereby supports cancer stem cell survival and chemoresistance." (PMID 41050674, 2025). "We previously showed that breast cancer and HCC share a common Notch3 molecular signature, leading us to hypothesize that Notch inhibition may also enhance the effects of atezolizumab in advanced HCC." (PMID 39766289, 2024). "The expressions of NOTCH3 and ZEB1 are negatively correlated in breast cancer." (PMID 38164285, 2024).
breast carcinoma (continued). "Interestingly, in most human mammary tumors, miR-221/222 are key breast cancer cell proliferation and invasion regulators and exert their effects via post-transcriptional regulation of STAT5A, and also suppress Notch3." (PMID 38124049, 2023). "Low expression of Notch3 and STAT5A predicted poorer prognosis of patients with breast cancer." (PMID 38124049, 2023). "Previous studies demonstrated anti-metastatic effects of Notch3, a transcription factor, through transcriptional up-regulation of p21, estrogen receptor-α (ERα), GATA-3, miR-488/FSCN1 and Kibra-mediated Hippo/YAP signaling in breast cancer epithelial cells." (PMID 38124049, 2023). "We investigated whether crosstalk existed between Notch3 and GSK3β in the progression of EMT in breast cancer." (PMID 36139447, 2022). "In addition, the expression levels of CPEB1, NOTCH3, NUAK1, and PDPK1 were significantly discrepant among the molecular subtypes of breast cancer." (PMID 36072578, 2022). "Furthermore, we showed that with high expression of Notch3 and PTEN had better RFS in breast cancer patients." (PMID 34006834, 2021). "Moreover, the mRNA expression of both Notch3 and PTEN predicted a better RFS for overall breast cancer patients." (PMID 34006834, 2021). "Notch3 and PTEN co-localized in the luminal MCF-7 and T-47D breast cancer cell lines." (PMID 34006834, 2021). "The WT N3ICD, the phosphodeficient (SA) mutant, or the phosphomimicking (SE) mutant were transiently overexpressed in MCF-7 and T47D luminal A breast cancer cells as well as in the derivatives of MCF-7 cells, in which the NOTCH3 or CSL genes had been knocked out by the CRISPR/Cas9 technique." (PMID 33775697, 2021). "Furthermore, in clinical data from luminal A subtype of breast cancer, PIM1 and NOTCH3 mRNA levels correlate positively." (PMID 33775697, 2021). "Notably, high mRNA expression of both Notch3 and PTEN predicted better relapse-free survival in overall breast cancer patients (P = 0.0065)." (PMID 34006834, 2021). "Thus, our data suggest that in the context of hormone-dependent breast cancer, PIM-mediated phosphorylation of Notch3 promotes tumor growth but via a different mechanism than phosphorylation of Notch1." (PMID 33775697, 2021). "In general, Notch3 expression positively correlated with elevated expression of PTEN, ER, lower Ki-67 index, and incidence of involved node status and predicted better recurrence-free survival in breast cancer patients." (PMID 34006834, 2021). "No major differences were detected between PIM1 and NOTCH3 mRNA expression levels in different breast cancer stages, whereas the PIM1 levels were reduced in most subtypes as compared with control samples." (PMID 33775697, 2021). "It was found that the increased Notch3 contributed to increased expression of miR-488, which further suppressed the expression of FSCN1, and corresponding proliferation, migration, and invasion of breast cancer cells." (PMID 33099573, 2020). "In contrast to Notch1 and 4, our previous study showed that Notch3 was mainly expressed in luminal breast cancer cells but not in either basal-like or HER2 (human epidermal growth factor receptor 2)-positive breast cancer cell line." (PMID 32636747, 2020). "Interestingly, in a phase I clinical study that was based on the administration of PF-06650808, an anti-NOTCH3 antibody-drug conjugate, the majority of responder patients had ER+/PR+/HER2- breast cancers." (PMID 32210163, 2020). "Ligand-independent activation of Notch3 in T-ALL has not been specifically investigated to our knowledge, but it has been reported to be significant in breast cancer, which, like T-ALL, is frequently associated with high Notch3 expression." (PMID 32210034, 2020). "Downregulation of Notch3 but not Notch1 considerably suppressed proliferation and induced apoptosis of the Erbb2-negative breast cancer cell lines implicating Notch3-mediated signaling in the proliferation of these cells." (PMID 32211044, 2020).